SLC6A2 (solute carrier family 6 member 2)
Diseases named in the same sentence as SLC6A2 in open-access papers:
SLC6A2 is named in the same sentence as 90 diseases in open-access papers, as found by Europe PMC text mining. Sharing a sentence is not in itself a finding about the gene and the disease. The quoted sentences say what the papers report.
depression (30 papers, 2013 to 2025). "Modern research has also found that SLC6A2 is associated with heart failure, depression, and hypertension." (PMID 40729010, 2025). "Gene SLC6A2 localizes to 16q12.2 which is associated with norepinephrine transport and bipolar disorder, depression and ADHD99–101." (PMID 38493193, 2024). "Major depressive disorder has also been associated with increased methylation levels of SLC6A2 in subjects with a history of exposure to stress early in life, such as childhood maltreatment (CM) or low socioeconomic status (SES) during adolescence." (PMID 34073101, 2021). "In patients with major depressive disorder, there seemed to be a relationship between the volume of the dorsolateral prefrontal cortex and polymorphism of the SLC6A2 G1287A gene." (PMID 28953935, 2017). "Earlier studies implicated norepinephrine transporter (NET) gene (SLC6A2) polymorphisms in the etiology of major depressive disorder (MDD)." (PMID 26960194, 2016). "As a potential mechanism, it has been proposed that reduced levels of SLC6A2 lead to dysfunction of serotonergic system by inhibiting serotonin uptake, which in turn may increase the susceptibility to depression." (PMID 34073101, 2021). "Nefazodone is an anti-depression drug, and the target genes/proteins of herb ingredients such as SLC6A2, ADRB2, MAOA are related to depression disorder." (PMID 33106157, 2020). "Β- caryophyllene and dibutyl phthalate could directly act on CHRM1, FAAH, CNR2, SLC6A2, and SLC6A3, which were associated with anesthesia, attention deficit hyperactivity disorder, and major depressive disorder." (PMID 40729010, 2025). "Indeed, different combinations of SLC6A2 polymorphisms may be associated with distinct sub-phenotypes of MDD; there was a dose relationship between the number of T containing genotypes and the presence of recurrent depression." (PMID 26960194, 2016).
attention deficit-hyperactivity disorder (11 papers, 2005 to 2025). A disorder characterized by a marked pattern of inattention and/or hyperactivity-impulsivity that is inconsistent with developmental level and clearly interferes with functioning in at least two settings (e.g. at home and at school). "SLC6A2 is involved in NE transport and is associated with the pathophysiology of attention-deficit/hyperactivity disorder (ADHD) in children." (PMID 31139205, 2019). "SLC6A2 gene has been examined in attention-deficit hyperactivity disorder because drugs that block the norepinephrine transporter are efficient in treating the disorder." (PMID 21674840, 2011).
Anxiety (10 papers, 2013 to 2025). Intense feelings of nervousness, tension, or panic often arise in response to interpersonal stresses. "Here we present evidence for the impact of genetic variation of microRNA regulation of SLC6A2 on the RDoC defensive motivational system in fear and anxiety." (PMID 30341278, 2018). "MicroRNAs regulate dynamic gene expression during synaptic plasticity and genetic variation of microRNAs modulating noradrenaline transporter gene (SLC6A2) expression may thus lead to altered central and peripheral processing of fear and anxiety." (PMID 30341278, 2018). "Our data thus give a first glimpse into molecular mechanisms by which MIR579 may act on endophenotypes as well as clinical phenotypes of fear and anxiety, e.g., by regulating not only SLC6A2 but also other genes involved in fear and anxiety." (PMID 30341278, 2018). "We could not differentiate between healthy controls and patient groups with stress related disorders and significantly higher levels of anxiety however, which suggests that age may actually be the more important factor determining the methylation status of the SLC6a2 promoter." (PMID 24312678, 2013). "SLC6A4, SLC6A2, and DRD2 are known to be involved in the serotonergic and dopaminergic systems, which impact the perception of exercise-induced fatigue and anxiety." (PMID 39200631, 2024). "In conclusion, microRNA regulation of SLC6A2 may contribute to the pathophysiology of fear and anxiety not necessarily by increased basic pathological anxiety but rather by modulating reactions of fear and flight." (PMID 30341278, 2018).
Hypertension (8 papers, 2013 to 2025). The presence of chronic increased pressure in the systemic arterial system. "The original studies which reported increased SLC6a2 promoter methylation in hypertension and panic disorder were performed in leukocytes." (PMID 24312678, 2013).
neuroendocrine tumors (7 papers, 2015 to 2025). "It is taken up into tumor cells by the norepinephrine transporter (NET, SLC6A2), which is highly expressed in neuroendocrine tumors." (PMID 37059009, 2023).
Obesity (6 papers, 2018 to 2026). Accumulation of substantial excess body fat. "Loss of Slc6a2 function in obese mice attenuates obesity, promotes lipolysis, and restores thermogenesis." (PMID 34613819, 2021). "For example, in obesity, SAMs in brown adipose tissue induce expression of solute carrier family 6 member 2 (SLC6A2) and monoamine oxidase A(MAOA)." (PMID 37020587, 2023). "Sympathetic neuron-associated macrophages (SAMs), a macrophage population involved in norepinephrine clearance via the transporter Slc6a2, are upregulated in the sympathetic fibers of obese mice—deletion of Slc6a2 gene rescues the thermogenic capacities and promotes fat browning in obesity." (PMID 38037591, 2023). "SAMs are also present in human sympathetic ganglia, possessing the same machinery (MAOA, SLC6A2), suggesting the mechanism is evolutionarily conserved, and therefore could be a viable anti-obesity therapeutic target." (PMID 34613819, 2021).
orthostatic intolerance (4 papers, 2013 to 2025). "Loss-of-function mutation in SLC6A2 causes a Mendelian syndrome characterized by orthostatic intolerance with tachycardia, resulting from decreased reuptake of norepinephrine and higher plasma concentrations." (PMID 30952858, 2019). "In addition, mutations in the SLC6A2 gene can lead to orthostatic intolerance, a syndrome characterized by dizziness, fatigue, altered consciousness, and syncope." (PMID 40729010, 2025).
colon cancer (3 papers, 2022 to 2025). "Among them, the most worthy of further research is α-selinene, targeting SLC6A2 to treat pain and neuropsychiatric disorders, and β-caryophyllene, to treat breast cancer and colon cancer." (PMID 40729010, 2025). "SLC6A2, also known as NAT1, has been found to be prognostic for colon cancer, and both in vivo and in vitro studies have linked expression to survival in many cancer types, including prostate and breast." (PMID 36199081, 2022).
congestive heart failure (3 papers, 2018 to 2022). Failure of the heart to pump a sufficient amount of blood to meet the needs of the body tissues, resulting in tissue congestion and edema. "Genetic SLC6A2 dysfunction is capable of triggering the postural tachycardia syndrome while the impaired function of cardiac SLC6A2 is familiar in a variety of organic heart disease such as ischemic heart disease, congestive heart failure, and stress-induced cardiomyopathy." (PMID 34456633, 2021).
panic disorder (2 papers, 2013 to 2021). An anxiety disorder characterized by multiple unexpected panic attacks with persistent concern of recurring attacks. "Extensive attempts to explain NET dysfunction in MDD and panic disorder by association with DNA sequence variation in the NET gene SLC6a2 have been inconclusive, yielding weak association results and rare functional sequence variation." (PMID 24312678, 2013). "In addition, a polymorphism in the promoter of the SLC6A2 gene (encoding NET) is associated with panic disorder and anxious arousal symptoms of PTSD." (PMID 34650410, 2021). "A previous report, based on pilot studies in leukocytes using methylation specific PCR (MSP), suggested that epigenetic silencing of the SLC6a2 gene by methylation of the promoter CpG island may underly NET dysfunction in patients with panic disorder.." (PMID 24312678, 2013). "An unambiguous biological marker such as SLC6a2 promoter methylation in a readily accessible tissue such as leukocytes would have high value in the diagnosis of complex diseases such as panic disorder and MDD." (PMID 24312678, 2013). "Based on these preliminary findings, a hypothesis was formed that with the development of panic disorder, the SLC6a2 promoter is hypermethylated, leading to transcriptional repression of the SLC6a2 gene." (PMID 24312678, 2013). "The objective of this study was to characterise the DNA methylation state of the SLC6a2 gene promoter in patients with MDD and panic disorder." (PMID 24312678, 2013).
anorexia nervosa (1 paper, 2018). A disorder most often seen in adolescent females characterized by a refusal to maintain a minimally normal body weight, an intense fear of gaining weight, a disturbance in body image, and, in postmenarcheal females, the development of amenorrhea. "SLC6A2 and SLC6A4 are associated not only with gastrointestinal disease, but also with anorexia nervosa, acute anxiety, and autism." (PMID 29861771, 2018).
asthma (1 paper, 2024). "SLC6A2 (NET) and SLC6A3 (DAT) are involved in neurotransmitter transport from the extracellular space into the intracellular compartment, influencing the autonomic regulation of airway tone, likely in asthma." (PMID 39100210, 2024).
creatine transporter deficiency (1 paper, 2021). X-linked creatine transporter deficiency (CRTR-D) is a creatine deficiency syndrome characterized clinically by global developmental delay/ intellectual disability (DD/ID) with prominent speech/language delay, autistic behavior and seizures. "In addition, the solute carrier family 6 member 2 (SLC6A2) gene localized in the QTL on BTA 18 is of interest due to the identification of a causal mutation for creatine transporter deficiency in humans." (PMID 34335696, 2021).
Dysmenorrhea (1 paper, 2025). Pain during menstruation that interferes with daily activities. "Six essential oil components could be associated with chronic pain, acute pain, musculoskeletal pain, visceral spasms, and dysmenorrhea by acting on four protein targets, including CHRM1, PTGS1, PTGS2, and SLC6A2." (PMID 40729010, 2025).
gastric ulcer (1 paper, 2018). An ulcerated lesion in the mucosal surface of the stomach.
Insulin resistance (1 paper, 2017). Increased resistance towards insulin, that is, diminished effectiveness of insulin in reducing blood glucose levels. "The association of SLC6A2 polymorphisms with NAFLD may be mediated through insulin resistance." (PMID 28953935, 2017).
Joubert syndrome (1 paper, 2020). Joubert syndrome (JS) is characterized by congenital malformation of the brainstem and agenesis or hypoplasia of the cerebellar vermis leading to an abnormal respiratory pattern, nystagmus, hypotonia, ataxia, and delay in achieving motor milestones. "SLC6A2 interacts with RPGRIP1L, a ciliary protein known to cause Joubert syndrome, MKS and bipolar disorder." (PMID 32973177, 2020).
preeclampsia (1 paper, 2021). Preeclampsia is a hypertensive disorder of pregnancy that is characterized by new-onset hypertension with proteinuria presenting after 20 weeks of gestation, and depending on mild or severe forms may initially present with severe headache, visual disturbances, and hyperreflexia. "The analysis of the final models points toward a relevance of AR, VDR, SLC6A2, NOS3 and CHRM4 as targets for preeclampsia." (PMID 33546161, 2021). "The most relevant targets for preeclampsia were: AR, VDR, SLC6A2, NOS3 and CHRM4, while ABCG2, ERBB2, CES1 and REN led to the most relevant off-targets." (PMID 33546161, 2021).
tumor (15 papers, 2010 to 2025). "Our analysis supports this link between the expression of key noradrenergic‐related genes, such as DBH, SLC6A2, and their downstream ADRA/ADRB receptors, with increased tumor severity in TCGA‐LIHC samples." (PMID 41347690, 2025). "Jude’s Human Tumor Atlas Project supported higher expression of ALK in ADRN and sympathoblast clusters and similar expression of SLC6A2 across ADRN/MES subtypes." (PMID 39825754, 2025).
cancer (6 papers, 2021 to 2024). A tumor composed of atypical neoplastic, often pleomorphic cells that invade other tissues. "Polymorphisms in SLC6A2 may also interact with smoking exposure to modulate the risk for tobacco-related cancers." (PMID 36199081, 2022). "Additional noteworthy findings from our analyses of all multiple primary cancers combined include cancer susceptibility signals in SAMHD1 and SLC6A2, both having a significantly higher risk being diagnosed with multiple cancers compared to single cancers." (PMID 36199081, 2022). "By reviewing previous studies, we found that there were fewer reports between SLC6A2 and tumors, but we found that CNR2 plays a role in multiple cancers." (PMID 33754011, 2021). "Furthermore, the putative novel miRNA EGCG-MDAMB231-5 targets MBP (Myelin Basic Protein), HIC1 (hypermethylated in cancer 1), and P3H2 (Prolyl 3-Hydroxylase 2), SLC6A2 (Solute Carrier Family 6 Member 2) genes." (PMID 36276982, 2022).
cardiovascular diseases (3 papers, 2015 to 2021). "Other clinical studies revealed genetic variations in the SLC6A2 gene are associated with neuropsychiatric and/or cardiovascular disease by way of polymorphism in the 3’ end by micro RNA mechanisms." (PMID 34650410, 2021).
neurodegenerative disease (3 papers, 2014 to 2024). A disorder of the central nervous system characterized by gradual and progressive loss of neural tissue and neurologic function. "This module contained 72 genes, including several that are implicated in neurodegenerative diseases, suggesting that critical LC genes (Dbh, Gal, Slc6a2) are clustering with neurodegeneration genes in their expression patterns after treatment with DSP-4." (PMID 36635251, 2023).
respiratory diseases (1 paper, 2025). "The “active component–target–disease” network further demonstrated these essential oil components’ potential efficacy against pain, tumors, neuropsychiatric diseases, eye diseases, and respiratory diseases, which were highly related to PPARA, GABRA1, PTGS2, and SLC6A2." (PMID 40729010, 2025).
skeletal dysplasia (1 paper, 2021). Any Mendelian diseases that affects growth and development of the skeleton. "SLC6A2 is responsible for three allelic skeletal dysplasias; (in increasing severity) diastrophic dysplasia, atelosteogenesis 2 and achondrogenesis type 1B." (PMID 34092239, 2021).
SLC6A2 also shares sentences with these, for which no sentence is quoted: neuroblastoma (22 papers); schizophrenia (6); Parkinson disease (5); paraganglioma (4); Alzheimer disease (3); bipolar disorder (3); Cognitive impairment (3); epilepsy (3); heart failure (3); mood disorder (3); neurological disorders (3); pheochromocytoma (3); psychiatric disorder (3); coronary artery disease (2); diabetes (2); Dystonia (2); hyperekplexia (2); insomnia (2); ovarian carcinoma (2); sleep disorder (2); adrenocortical adenoma (1); adrenocortical carcinoma (1); Akinesia (1); alcohol dependence (1); alcoholism (1); anxiety disorder (1); autism (1); autism spectrum disorder (1); breast carcinoma (1); carcinoid (1).
A further 36 diseases each share a sentence with SLC6A2 in 1 paper.